TARS3 (threonyl-tRNA synthetase 3)
Description:
Catalyzes the attachment of threonine to tRNA(Thr) in a two-step reaction: threonine is first activated by ATP to form Thr-AMP and then transferred to the acceptor end of tRNA(Thr). Also edits incorrectly charged tRNA(Thr) via its editing domain, at the post-transfer stage.
Synonyms: TARSL2; FLJ25005; ThrRS-L
Tractability: PROTAC: ubiquitination databases record sites on it.
Gene: Protein-coding gene on chromosome 15 (101,653,596 to 101,724,565, reverse strand). Ensembl gene ENSG00000185418.
Subcellular location: Cytoplasm; Nucleus
Subcellular location (Human Protein Atlas): Cytosol
Gene Ontology:
Molecular function: protein binding; threonine-tRNA ligase activity; aminoacyl-tRNA ligase activity; ATP binding; nucleotide binding
Biological process: threonyl-tRNA aminoacylation; tRNA aminoacylation; tRNA aminoacylation for protein translation
Cellular component: cytoplasm; nucleus
Genetic constraint (gnomAD): Loss-of-function variants: 64 observed, 72.14 expected, observed/expected ratio (o/e) 0.89, 90% interval 0.72 to 1.09. The synonymous counts are far from expectation, so gnomAD's model fits this gene poorly and the ratio says little. Missense variants: 757 observed, 769.93 expected, observed/expected ratio (o/e) 0.98, 90% interval 0.93 to 1.04. Synonymous variants: 340 observed, 273.5 expected, observed/expected ratio (o/e) 1.24, 90% interval 1.14 to 1.36.
Homologues: Orthologues: chimpanzee TARS3 (99% identical), macaque TARS3 (96% identical), dog TARS3 (88% identical), mouse Tars3 (85% identical), rat Tars3 (85% identical), guinea pig TARS3 (79% identical), rabbit TARS3 (78% identical), pig TARS3 (73% identical), Drosophila melanogaster ThrRS (59% identical), Caenorhabditis elegans tars-1 (52% identical). Paralogues in human: TARS1 (65% identical), TARS2 (47% identical), PARS2 (12% identical), MRPL39 (10% identical).
Diseases named in the same sentence as TARS3 in open-access papers:
TARS3 is named in the same sentence as 1 disease in open-access papers, as found by Europe PMC text mining. Sharing a sentence is not in itself a finding about the gene and the disease.
TARS3 shares sentences with these, for which no sentence is quoted: viral infection (1 paper).